BRIP1 (BRCA1 interacting DNA helicase 1)
Diseases named in the same sentence as BRIP1 in open-access papers (continued):
Sharing a sentence is not in itself a finding about the gene and the disease.
colon cancer (9 papers, 2016 to 2025). "Survival analysis showed that low BRIP1 expression was associated with poorer overall survival in both rectal and colon cancers significantly." (PMID 41597333, 2025). "In colon cancer, BRIP1 expression showed significant associations with several clinicopathological parameters, including gender, lymphatic invasion, CEA levels, pathological stage, M stage, N stage, MSI status, and anatomic tumor location." (PMID 41597333, 2025). "We describe here two patients with colon cancer who were found to have a BRIP1 mutation in tumor tissue which was subsequently identified in the germline and postulate that germline BRIP1 mutations confer an increased risk of colorectal cancer." (PMID 31064327, 2019). "We describe two patients with colon cancer whose tumor tissue were found to harbor BRIP1 mutations on analysis by next-generation sequencing." (PMID 31064327, 2019). "These case reports highlight a previously unreported association of BRIP1 germline mutations with colon cancer predisposition." (PMID 31064327, 2019). "Similarly, in colon cancer, high BRIP1 expression was associated with improved survival outcomes (2975.55 ± 222.49 vs. 2421.43 ± 206.15 days; χ2 = 7.304; p = 0.007)." (PMID 41597333, 2025). "Likewise, INHBA plays an immunomodulatory role in colon cancer, and BRIP1 is related to the susceptibility of colon cancer." (PMID 33836755, 2021). "Overall survival analysis indicated that BRIP1 expression had significant prognostic value in both rectal and colon cancer." (PMID 41597333, 2025). "In colon cancer, BRIP1 expression was correlated with gender, lymphatic invasion, carcinoembryonic antigen (CEA) level, pathological stage, M stage, N stage, microsatellite instability (MSI) status, and anatomical tumor location." (PMID 41597333, 2025). "One 54‐year‐old male patient had a germline mutation in the BRIP1 (BRCA1 interacting protein C‐terminal helicase 1) gene, which is known to increase the risk of ovarian, breast, and colon cancers." (PMID 33350171, 2021). "The BRIP1 missense variant c.2477A>G, p.(Asn826Ser), was identified in patient OC11, diagnosed with HGSOC at the age of 39 years and family history of colon cancer and lymphoma." (PMID 33008098, 2020). "Based on our literature review, the association of BRIP-1 mutations with colon cancer has not been previously reported." (PMID 31064327, 2019).
gastric cancer (9 papers, 2013 to 2026). A primary or metastatic malignant neoplasm involving the stomach. "A connection between BRIP1 mutations and gastric cancer has been reported specifically in female patients." (PMID 40282418, 2025). "Interestingly, the two gastric cancers harboured different BRIP1 mutations, but conversely, both patients were women diagnosed in their seventies who met the CRC criteria." (PMID 40282418, 2025). "ZKSCAN1 (also known as KOX18, ZNF139), a node with three connections in the same module with BRIP1, also has been reported to play regulatory roles in migration and invasion of human gastric cancer cells." (PMID 30240439, 2018). "To assess the therapeutic relevance of BRIP1 in gastric cancer (GC), we examine its functional role in conferring resistance to anoikis within GC cells and elucidate the oncogenic signaling pathways modulated by BRIP1." (PMID 41828629, 2026). "Additionally, five HGSCs, one uncharacterized gynaecological cancer and two gastric cancers were the other types of cancer developed by BRIP1-positive patients." (PMID 40282418, 2025). "Remarkably, an excess of gastric cancers was displayed in BRIP1 families." (PMID 40282418, 2025). "Moreover, overexpression of BRIP1 is a prognostic biomarker for breast and gastric cancers." (PMID 41303409, 2025). "Conversely, high expression of BRIP1 was correlated to better OS (P=0.024), FP (P<0.01), and PPS (P<0.001) prognosis for gastric cancer." (PMID 36907870, 2023).
lung carcinoma (9 papers, 2015 to 2024). "In our lung cancer patient cohort, BRIP1 (p.W448X) and MPL (c.981-1G > C) germline mutations were detected." (PMID 35428225, 2022). "Case–control analysis showed SBDS c.184A>T(p.K62*), TSHR c.1574T>C(p.F525S), BRIP1 (BRCA1 interacting helicase 1) c.1018C>T(p.L340F), and MUTYH (mutY DNA glycosylase) c.55C>T(p.R19*) were significantly associated with increased lung cancer risk (q value < 0.05)." (PMID 37885353, 2024). "Similarly, high BRIP1 expression was linked to the poor OS, FP (first progression), and PPS (P<0.001 for all) prognosis for lung cancer." (PMID 36907870, 2023). "Moreover, we observed, particularly in breast, brain and lung cancer cohorts, a strong negative correlation between ALDH2 and BRIP1." (PMID 34454516, 2021).
cervical cancer (8 papers, 2014 to 2025). A primary or metastatic malignant neoplasm involving the cervix. "BRIP1 gene single nucleotide polymorphism could affect the susceptibility of cervical cancer, and BRIP1 gene mutation was closely related to the occurrence and development of cervical cancer." (PMID 39211736, 2024). "In addition, the association between BRIP1 mutations and the development of breast, ovarian, and cervical cancers has been reported." (PMID 36907870, 2023). "BRIP1 was lowly expressed in cervical cancer tissues compared with normal cervical tissues and was closely related to poor prognosis." (PMID 39211736, 2024). "Thus, cervical cancers with BRIP1 and WRN alterations may be affected by PARP inhibitors." (PMID 36333792, 2022). "The overexpression of BRCA1, BRCA2, RAD51, BRIP1 (BACH1), FANCD2, BLM and RFC in non-responding versus responding cervical cancer samples suggests that DNA repair mechanism activation occurs through cell cycle arrest and homologous recombination." (PMID 24708616, 2014). "Immunohistological staining confirmed increased expression of BRCA1, BRIP1, FANCD2 and RAD51 in non-responsive compared with responsive advanced squamous cervical cancer, both in the initial set of 21 cervical cancer samples and the second set of 24 samples." (PMID 24708616, 2014).
colorectal cancer (8 papers, 2013 to 2025). A primary or metastatic malignant neoplasm that affects the colon or rectum. "This study demonstrated that BRIP1 expression is significantly associated with key clinicopathological features and overall survival in colorectal cancer based on TCGA analyses." (PMID 41597333, 2025). "Dysregulation of BRIP1 can lead to genomic instability, a hallmark of colorectal cancer progression." (PMID 41597333, 2025). "In this study, we evaluated the clinical relevance and potential prognostic association of BRIP1 expression in colorectal cancer using TCGA datasets and an independent cohort of 60 CRC patients." (PMID 41597333, 2025). "Colorectal cancer development in carriers of BRIP1 gene variants has been reported and a similar occurrence was observed in our patient’s pedigree." (PMID 37277882, 2023). "BRIP1 was found mutated in two cases: one woman had OC and relatives with BC, while the other one had BC at 42 years of age and positive family history for early-onset BC, PrC, brain, and colorectal cancer." (PMID 32957588, 2020). "We present two case reports and hypothesize that patients with BRIP1 (BRCA1 Interacting Protein C- terminal helicase 1) gene mutations have an increased risk of colorectal cancer." (PMID 31064327, 2019). "Third, while our findings suggest a prognostic association, functional studies are required to elucidate the mechanistic role of BRIP1 in colorectal cancer progression." (PMID 41597333, 2025). "Such integrative approaches may ultimately establish BRIP1 as a clinically actionable biomarker in colorectal cancer." (PMID 41597333, 2025). "This study investigated the clinical and prognostic value of BRIP1 in colorectal cancer (CRC)." (PMID 41597333, 2025). "However, the biological and clinical significance of BRIP1 expression in colorectal cancer remains poorly characterized, and data regarding its prognostic relevance are limited." (PMID 41597333, 2025). "Collectively, our results suggest that BRIP1 expression may have potential prognostic relevance in colorectal cancer; however, these findings should be interpreted as exploratory." (PMID 41597333, 2025). "Taken together, these findings suggest that transcript-level alterations of BRIP1 alone may capture clinically meaningful prognostic information in colorectal cancer." (PMID 41597333, 2025). "We have also identified a PV in BRIP1 gene in a patient presenting with colorectal cancer." (PMID 34326862, 2021).
breast tumor (6 papers, 2014 to 2024). "Among a number of differentially expressed genes, BRIP1, showing a fivefold up‐regulation, was identified as a potential gene that might underpin breast tumour progression." (PMID 32888398, 2020). "Our siRNA experiments suggest that BRIP1 up‐regulation may promote breast tumour metastasis." (PMID 32888398, 2020). "The gene expression investigations revealed the substantial down-regulation of BRCA1 (P = 0.02), CHEK2 (P = < 0.0001), BRIP1 (P = < 0.0001), and RAD51 (P = 0.01) in breast tumors compared with adjacent normal tissues." (PMID 35715772, 2022).
hereditary ovarian cancer (6 papers, 2015 to 2023). "The gene test of this patient showed mutations of uncertain significance in FANCA, BRCA1, and BRIP1, which have been associated with hereditary ovarian cancers." (PMID 34941061, 2021). "Moreover, variants in BRIP1 are also linked to an increased risk of hereditary ovarian cancer." (PMID 38003901, 2023). "Two-hit inactivation has also been described, in smaller case series, for PALB2- and ATM-related HBC, and BRIP1-related hereditary ovarian cancer." (PMID 32295625, 2020).
sarcoma (6 papers, 2021 to 2025). A usually aggressive malignant neoplasm of the soft tissue or bone. "In the presented case, a complete remission with olaparib was observed for a patient with metastatic high-grade pleomorphic sarcoma with a germline BRIP1-mutation." (PMID 40988318, 2025). "We here describe the first case of a metastatic BRIP1-mutated sarcoma, undergoing a complete radiologic response to olaparib treatment." (PMID 40988318, 2025). "We present a case of response and long-term complete remission under treatment with the poly(ADP-ribose) polymerase inhibitor (PARP-inhibitor) olaparib in a patient with meta-static high-grade pleomorphic sarcoma, with an next generation sequencing detected BRIP1-mutation." (PMID 40988318, 2025). "Besides, the results of pooling analysis in the ONCOMINE database also verified that BRIP1 is highly expressed in breast, sarcoma, colorectal, and head and neck cancers." (PMID 36907870, 2023).
triple-negative breast carcinoma (6 papers, 2016 to 2023). An invasive breast carcinoma which is negative for expression of estrogen receptor (ER), progesterone receptor (PR), and human epidermal growth factor receptor 2 (HER2). "Out of the genes that have a role in the BRCA1/2 HR pathway, NCCN Guidelines (version 2.2021) indicate that the risk of triple negative breast cancer is potentially increased in patients with P/LP variants in BRIP1, RAD51C and RAD51D." (PMID 35710434, 2022). "In this study, we presented the fundamental role of BRCA1 interactors BRIP1 and RAD50 in the development of differential severity in triple-negative breast cancer (TNBC) among various affected individuals." (PMID 36873936, 2023).
endometrial cancer (5 papers, 2014 to 2025). Primary or metastatic malignant neoplasm involving the endometrium (mucous membrane that lines the endometrial cavity). "What’s more, recent investigations indicated Olaparib monotherapy had the potential in treating endometrial cancers with BRIP1 mutations." (PMID 36932143, 2023). "In endometrial cancer, BRIP1 correlated to tumor recurrence and patients with mutations in BRIP1 might benefit from poly ADP-ribose polymerase (PARP) inhibitors." (PMID 37153833, 2023). "The discovery of novel variants in BRIP1, MLH1, and PIK3R1 further challenges the current understanding and suggests that endometrial cancer may involve a broader array of genetic alterations than previously recognized." (PMID 39296440, 2024). "The identification of novel variants in genes such as ARID1A, BRIP1, MLH1, PIK3R1, and PTEN expands the understanding of the genetic basis of endometrial cancer, suggesting that a broader spectrum of mutations may contribute to the disease than previously recognized." (PMID 39296440, 2024).
glioma (5 papers, 2016 to 2026). A benign or malignant brain and spinal cord tumor that arises from glial cells (astrocytes, oligodendrocytes, ependymal cells). "BRIP1 was found to be an independent signature, which was correlated with worse prognosis in glioma." (PMID 32047515, 2019). "Blood–brain barrier penetrant PARP inhibitors may be effective in glioma patients carrying GVs in ATM, BRCA2, BRIP1, FANCA, and SDHA identified here that are associated with HRR deficiency, and may act synergistically with radio-, chemo-, and immunotherapy." (PMID 41546701, 2026).
hereditary cancer syndromes (5 papers, 2020 to 2025). "Additionally, CHEK2-Associated Hereditary Cancer Syndrome and cancer predisposition associated with BRIP1 mutations may represent conditions with a potential association with MM risk." (PMID 41331641, 2025).
lung adenocarcinoma (5 papers, 2016 to 2023). A carcinoma that arises from the lung and is characterized by the presence of malignant glandular epithelial cells. "Moreover, a positive correlation was observed between BRIP1 expression and the immune infiltration levels of cancer-associated fibroblasts and CD8+ T cells in lung adenocarcinoma." (PMID 36907870, 2023). "Additionally, BRIP1 tends to be coexpressed with PD-L1 in lung adenocarcinoma." (PMID 36324591, 2022). "The result showed that the methylation of BRIP1 was only downregulated in lung adenocarcinoma (LUAD) and BRCA while none cancer type upregulated the level methylation of BRIP1." (PMID 36932143, 2023).
serous ovarian cancer (5 papers, 2016 to 2025). "Approximately 50% of high-grade serous ovarian cancers are characterized by HR deficiency, which involves mutations in BRCA1/2, the MRN complex (MRE11, RAD50, NBS1), ATM, RAD51C/D, PALB2, BRIP1, BARD1, and other genes." (PMID 31572446, 2019). "For example, susceptibility to high-grade serous ovarian cancer (HGSOC) is driven by mutations in genes that are involved in DNA double strand break repair (BRCA1, BRCA2, BRIP1, RAD51D and RAD51C), and as a consequence these tumors are highly genomically unstable." (PMID 28881617, 2017).
breast invasive carcinoma (4 papers, 2017 to 2024). "Among the top ten, we found BRCA1-interacting protein C-terminal helicase 1 (BRIP1), whose low-expression level was associated with improved overall survival in breast invasive carcinoma patients." (PMID 28317894, 2017). "Single-nucleotide and copy number variations of BRIP1 were noticed in multiple cancers, and the expression of BRIP1 is significantly regulated by copy number variation in breast invasive carcinoma and lung squamous cell carcinoma." (PMID 36907870, 2023). "Rad51, NEIL3 and BLM, which were linked to invasive breast cancer and BRIP1 that was associated with IDC and LC, are the only genes to our knowledge that were previously linked to invasive breast carcinoma." (PMID 33662042, 2021).
ataxia telangiectasia (3 papers, 2013 to 2021). Ataxia-telangiectasia is the association of severe combined immunodeficiency (affecting mainly the humoral immune response) with progressive cerebellar ataxia. "Seven of these patients were found to carry two pathogenic variants including one biallelic ATM carrier with a clinical diagnosis of ataxia-telangiectasia, two ATM/BRCA2 carriers, one BRIP1/BRCA2 carrier, one BRCA1/CHEK2 carrier, one BARD1/PALB2 carrier, and one CHEK2/PALB2 carrier." (PMID 28008555, 2017).
Fanconi anemia complementation group (3 papers, 2007 to 2025). "BRIP1 (BRCA1-interacting protein 1), also called BACH1 (BRCA1-associated C-terminal helicase-1) and FANCJ (Fanconi anemia complementation group J), belongs to the DEAH helicase family." (PMID 17342202, 2007).
meningioma (3 papers, 2017 to 2022). A generally slow growing tumor attached to the dura mater. "Interestingly, specific polymorphisms affecting genes such as caspase 8, NF2, XRCC1, and BRIP1 are related to increased risk for meningioma rise." (PMID 35891812, 2022).
squamous cervical cancer (3 papers, 2014 to 2024). "Therefore, our findings demonstrate that baseline FANCD2, RAD51, BRCA1 and BRIP1 nuclear protein expression could have an important role in treatment failure in advanced squamous cervical cancer." (PMID 24708616, 2014). "Particularly for CC, BRIP1 was found to be overexpressed in advanced squamous cervical cancer biopsies of non-responsive to base-line therapy patients, as compared to biopsies of responsive patients." (PMID 27415837, 2016).
colorectal adenocarcinoma (2 papers, 2021 to 2024). The most common type of colorectal carcinoma. "The patient (II-1) with the BRIP1 PV (c.2392C>T; p.(Arg798*)) developed colorectal adenocarcinoma at 61 years and ovarian serous carcinoma at 64 years." (PMID 34026625, 2021).
glioblastoma (2 papers, 2023 to 2024). The most malignant astrocytic tumor (WHO grade IV). "We replicated most of these associations in glioblastoma (Klughammer cohort) where 14 of 17 genes were also positively associated with TERT expression, including four genes related to DNA repair (XRCC2, MSH5, TRAIP, BRIP1)." (PMID 37418389, 2023).
hereditary colorectal cancer (2 papers, 2023). "Recent publications evaluated the role of the BRIP1 variant in hereditary colorectal cancer." (PMID 36932143, 2023).
Infertility (2 papers, 2024 to 2025). "Simultaneous administration of paclitaxel and carboplatin caused cumulative ovarian damage and infertility in mice with BRIP1 (BRCA1-interacting protein C-terminal helicase-1) mutations." (PMID 38927992, 2024).
Neuroendocrine tumors (2 papers, 2018 to 2025). "Another gene also had a significant association with a neoplasm-related phecode: BRIP1 with phecode 209 (“Neuroendocrine tumors,” p = 2.8 × 10−7, OR = 24)." (PMID 39799398, 2025).
ovarian tumors (2 papers, 2020 to 2022). "The presence of pathogenic germline variants in BRIP1 has been specifically related to ovarian tumors." (PMID 33134171, 2020). "Beyond these mutations, germline or somatic aberrations in genes of the homologous recombination (HR) pathway such as RAD51B/C/D, PALB2, ATM, BRIP1 may confer an HR deficiency in up to 50% of ovarian tumors." (PMID 36531003, 2022).